PDIA4 (protein disulfide isomerase family A member 4)
Diseases named in the same sentence as PDIA4 in open-access papers (continued):
Sharing a sentence is not in itself a finding about the gene and the disease.
diabetes (6 papers, 2017 to 2024). "Taken together, the loss‐of‐function data suggest that Pdia4 is a key regulator for β‐cell pathogenesis and diabetes." (PMID 34542937, 2021). "Pdia4 has been reported to be a novel ER chaperone implicated in β-cell pathogenesis in diabetes." (PMID 36935456, 2023). "Of note, Pdia4 deficiency and inactivation also improved β‐cell failure and diabetes." (PMID 34542937, 2021). "Our previous seminal paper showed the regulation of β-cell pathology and diabetes by Pdia4 in db/db mice." (PMID 36935456, 2023). "This seminal publication identified Pdia4 as a novel therapeutic target of β-cell pathogenesis and diabetes as a result of ROS dysregulation." (PMID 36935456, 2023). "Taken together, this work demonstrates that PS1 negatively regulated β-cell pathogenesis and diabetes via reduction of ROS production involving the Pdia4/Ndufs3 and Pdia4/p22 cascades." (PMID 36935456, 2023). "As a result, Pdia4 ablation accumulated functional β-cells and, in turn, reversed diabetes in diabetic animals." (PMID 36935456, 2023). "Here, we investigated the function and mechanism of PS1, a Pdia4 inhibitor, in β-cells and diabetes." (PMID 36935456, 2023). "Overall, we believe the data presented herein move us one step further towards clinical use of the Pdia4-based therapy for β-cell pathogenesis and diabetes." (PMID 36935456, 2023). "Pdia4 has been characterized as a key protein that positively regulates β-cell failure and diabetes via ROS regulation." (PMID 36935456, 2023). "Recent study indicated that PDIA4 was distributed in the nuclei, cytosol, membrane, mitochondria, and ER of Min6 β-cells and serum PDIA4 also went up with diabetes development in HFD-fed B6 mice, and diabetic patients." (PMID 36619574, 2022). "PDIA4 function has been shown to improve diabetes, lower blood sugar, glycated hemoglobin (HbA1C) and reactive oxygen species (ROS), and increase insulin secretion." (PMID 36619574, 2022). "A 2021 study utilized a mouse model to explore the role of protein disulfide isomerase family A, member 4 (Pdia4), in the regulation and dysfunction of β-cells and the role it plays in the development of diabetes." (PMID 36012526, 2022). "Medications targeting the POMC-MCR pathway, the traditional diabetes drug metformin, and the molecule Pdia4 are all current research interests." (PMID 36012526, 2022). "This work unraveled the molecular mechanism through which Pdia4 resulted in a decrease in functional β‐cell mass during diabetes." (PMID 34542937, 2021). "Both models of diabetes complemented each other and revealed the importance and therapeutic potential of Pdia4 for diabetes and β‐cell failure." (PMID 34542937, 2021). "Collectively, the data on Pdia4 overexpression suggest that Pdia4 promotes β‐cell pathogenesis and diabetes." (PMID 34542937, 2021). "Equally importantly, serum Pdia4 also went up with diabetes development in Leprdb/db mice, high‐fat diet (HFD)‐fed B6 mice, and diabetic patients." (PMID 34542937, 2021). "First, Pdia4 ablation led to a remarkable reduction in diabetes incidence (58%) in Pdia4−/−Leprdb/db mice aged 24 weeks (Pdia4−/−Leprdb/db)." (PMID 34542937, 2021). "Pdia4 transgenic (Pdia4tg/tg) mice on B6, BKS, and Leprdb/db backgrounds, which expressed a high level of transgenic Pdia4 in islets, were created and monitored for diabetes." (PMID 34542937, 2021). "The role of Pdia4 in HFD‐fed B6 mice was further verified because this model resembles human diabetes more closely than Leprdb/db mice in terms of disease etiology." (PMID 34542937, 2021). "The reversal of diabetes in aged Pdia4−/−Leprdb/db mice most probably came from reduced β‐cell death by Pdia4 and/or replenishment of β‐cells." (PMID 34542937, 2021). "Of note, Pdia4−/−Leprdb/db mice showed more effective amelioration of diabetes than the age‐matched Leprdb/db mice as shown by water consumption (right), PBG, glucose tolerance, islet preservation, survival rate (top), and life span (bottom)." (PMID 34542937, 2021).
diabetes (continued). "Conversely, Pdia4 inhibitor reversed diabetes via decreased β‐cell pathology and ROS production in diabetic animals." (PMID 34542937, 2021). "In parallel, a gain‐of‐function approach was taken to confirm the role of Pdia4 in diabetes development." (PMID 34542937, 2021). "The remainder of the study concentrated on the investigation of Pdia4 in β‐cell pathogenesis and diabetes." (PMID 34542937, 2021). "Conversely, Pdia4 overexpression accelerated diabetes in Pdia4tg/tgLeprdb/db mice and HFD‐fed Pdia4tg/tg B6 mice." (PMID 34542937, 2021). "Given that Pdia4 was implicated in the increase of ROS generation and islet atrophy during diabetes, we next investigated cell death of pancreatic islets in WT, Pdia4−/−, and Pdia4tg/tg BKS mice." (PMID 34542937, 2021). "Overall our work can be viewed as follows: excess nutrients/hyperglycemia → Pdia4 → Ndufs3 and p22phox → ROS → β‐cell failure and diabetes." (PMID 34542937, 2021). "Consistently, Pdia4−/−Leprdb/db mice, given 6.8 g feed/day/mouse from 4 to 24 weeks of age, showed completely arrested diabetes development (Pdia4−/−Leprdb/db + FR)." (PMID 34542937, 2021). "Strikingly, all the Pdia4−/−Leprdb/db mice became diabetes‐free by the age of 55 weeks and beyond, which correlated with decreased food intake in aged mice." (PMID 34542937, 2021). "Overall we believe the data presented provide conceptual advances in Pdia4 research and the application of β‐cells and diabetes." (PMID 34542937, 2021). "Enrichment of Pdia4 in the β‐cells of mice resulted in accelerated diabetes development and failure to accrue islet mass." (PMID 34542937, 2021). "Pdia4, a protein disulfide isomerase, is identified as a crucial regulator of β‐cell pathogenesis and diabetes." (PMID 34542937, 2021). "Leprab/db mice and HFD‐fed B6 mice were used as mouse models of diabetes to study the significance of Pdia4 in β‐cell failure and diabetes because Leprab/db mice develop severe diabetes while B6 mice fed a high‐fat diet develop moderate diabetes." (PMID 34542937, 2021). "Ablation of Pdia4 alleviated diabetes as shown by reduced islet destruction, blood glucose and HbA1c, reactive oxygen species (ROS), and increased insulin secretion in diabetic mice." (PMID 34542937, 2021). "The up‐regulation of Pdia4 in pancreatic islets correlated well with diabetes development in Leprdb/db mice and Lepob/ob mice, two spontaneous mouse models of diabetes." (PMID 34542937, 2021). "Next, mice with Pdia4 knockout and overexpression were generated to evaluate the impact of Pdia4 on β‐cell pathogenesis and diabetes." (PMID 34542937, 2021). "We hypothesized that PS1, a drug candidate that inhibits Pdia4, could reverse β-cell pathogenesis and diabetes in db/db mice." (PMID 36935456, 2023). "Besides, ablating PDIA4 reduced the symptoms of diabetes, such as elevated blood sugar and HbA1C levels, in diabetic mice." (PMID 36619574, 2022). "Furthermore, we generated islet‐specific Pdia4 knockout mice (Pdia4f/fLeprdb/dbCretg/0) to verify the islet‐specific function of Pdia4 in islets and diabetes." (PMID 34542937, 2021). "However, like other Pdis, nothing is known about the role of Pdia4 in diabetes, and its therapeutic potential and molecular basis in diabetes has not been deciphered." (PMID 34542937, 2021). "Furthermore, this work presents a compelling case for the further investigation of Pdia4 as a crucial player of β‐cell pathogenesis and diabetes." (PMID 34542937, 2021). "The fact that the Pdia4 expression increased with diabetes development in mice and humans prompted us to examine whether it could trigger β‐cell pathogenesis and diabetes." (PMID 34542937, 2021). "Targeting Pdia4 and its pathways may thus constitute attractive approaches for the treatment of β‐cell pathogenesis and diabetes." (PMID 34542937, 2021). "We demonstrated that Pdia4 positively regulated β‐cell dysfunction/death during diabetes." (PMID 34542937, 2021).
diabetes (continued). "Finally, we checked whether Pdia4 inhibitors could rescue β‐cells from death and, in turn, reverse diabetes in diabetic mice." (PMID 34542937, 2021). "We conceptualized these findings as follows: under pathological conditions, excessive Pdia4 and ROS led to β‐cell failure and diabetes; conversely, Pdia4 ablation and inhibition diminished ROS content in β‐cells and, thereby, reduced β‐cell failure and diabetes development." (PMID 34542937, 2021). "In good agreement with the publication on Pdia4 ablation, 16-week administration of PS1 alone and together with metformin normalized diabetes in db/db mice as shown by blood glucose, HbA1c, GTT, diabetic incidence, and water consumption." (PMID 36935456, 2023). "Closer analysis revealed that 58% of the Pdia4−/−Leprdb/db mice whose PBG was 137 mg/dl by 24 weeks of age, were diabetes‐free (Pdia4−/−Leprdb/db) compared to the rest (42%) which exhibited slight diabetes with PBG around 340 mg/dl (Pdia4−/−Leprdb/db)." (PMID 34542937, 2021). "In this study, monotherapy and combinational therapy of PS1, a Pdia4-based drug candidate with an IC50 of 4 μM, could lessen β-cell failure and, in turn, diabetes development in db/db mice." (PMID 36935456, 2023). "Overall, the data indicated that the Pdia4 inhibitor, PS1, alone and in combination, could treat and reverse diabetes." (PMID 36935456, 2023). "Although the concept of ROS causing β‐cell failure is not a new concept, the participation of Pdia4 in the Ndufs3 and p22Phox pathways gives greater understanding of the progression from oxidative stress to β‐cell pathology and diabetes." (PMID 34542937, 2021). "However, HFD‐fed Pdia4tg/tg B6 mice developed moderate diabetes as evidenced by BG, HbA1c, GTT, and diabetic incidence in comparison with HFD‐fed WT and Pdia4−/− B6 mice." (PMID 34542937, 2021). "WT and Pdia4−/− mice on B6 and BKS backgrounds were diabetes‐free." (PMID 34542937, 2021).
renal cell carcinoma (6 papers, 2023 to 2025). "Protein disulfide isomerase A4 (PDIA4) confers resistance to ferroptosis via induction of ATF4/SLC7A11 in renal cell carcinoma." (PMID 38095762, 2024). "PDIA4 inhibits ferroptosis in renal cell carcinoma through the PERK/ATF4/SLC7A11 signaling pathway." (PMID 39544949, 2024).
lung carcinoma (5 papers, 2020 to 2025). "Conversely, in lung cancer, PDIA4 deficiency has been reported to enhance cell proliferation and migration, presenting a stark contrast to our findings." (PMID 41185082, 2025). "The expression level of PDI was increased in lung cancer, and its members PDIA4 and PDIA6 were up-regulated in response to cisplatin treatment." (PMID 37315289, 2023). "Here, we first investigated the expression of host Pdia4 in the cancer stroma and its expression up‐regulation during lung cancer development." (PMID 35170261, 2022). "First, we investigated the link between Pdia4 expression level and lung cancer in human clinical samples." (PMID 35170261, 2022). "The overall data indicated that the Pdia4 RNA level in lung cancer tissues was negatively correlated with survival of patients as shown by survival rate and median survival time." (PMID 35170261, 2022). "We first confirmed that the Pdia4 level in lung cancer and other cancer types (brain cancer, renal carcinoma, melanoma and colorectal cancer) was inversely correlated to patient survival." (PMID 35170261, 2022). "Here, we first found that Pdia4 expression in lung cancer was negatively correlated with patient survival." (PMID 35170261, 2022). "During tumourigenesis, tumourigenic signals such as Cxcl1 and Ccl2 induce Pdia4 overexpression and Stat3 phosphorylation and, subsequently, lead to an up‐modulation of Vegf proteins in lung cancer stromata." (PMID 35170261, 2022). "Genetics studies in tumour‐bearing wild‐type and Pdia4–/– mice showed that host Pdia4 promoted lung cancer development in the mice via cancer stroma." (PMID 35170261, 2022). "Collectively, the data showed the importance of B and T cells for host Pdia4‐mediated lung cancer development." (PMID 35170261, 2022). "In sharp contrast, Pdia4 and CD45 were highly expressed in lung cancer tissues compared to healthy lung (Pdia4 and CD45)." (PMID 35170261, 2022). "Since host Pdia4 in T and B lymphocytes was pivotal for lung cancer development, we then addressed how Pdia4 controlled Stat3‐mediated expression of the Vegf family in both lymphocytes." (PMID 35170261, 2022). "To differentiate the Pdia4 expression in cancer stroma and lung cancer, we used anti‐CD45 antibody to stain stromal leukocytes." (PMID 35170261, 2022). "For the first time, we showed that Pdia4 expression was induced in lung cancer stroma of human and mouse origin." (PMID 35170261, 2022). "We also found that Pdia4 activated Stat3 and its downstream pathways (e.g., increased expression of Vegf family), leading to a promotion of lung cancer development in mice." (PMID 35170261, 2022). "Strikingly, Pdia4 reduction in lung cancer prolonged the median survival time by 38 months, which was very significant for lung cancer patients." (PMID 35170261, 2022). "Apparently, the Pdia4/Stat3/Vegf axis in T and B lymphocytes seemed to be important for lung cancer development." (PMID 35170261, 2022). "Next, we characterized the role of host Pdia4 in cancer development using lung cancer‐bearing wild‐type (WT) and Pdia4–/– mice on the B6 and Rag1–/– backgrounds." (PMID 35170261, 2022). "Genetics studies in WT and Pdia4–/– mice with lung cancer and other cancers (melanoma and colorectal cancer) showed that host Pdia4 in the cancer stroma regulated cancer development." (PMID 35170261, 2022). "Another study suggests that inhibition of PDIA4 ameliorates cisplatin resistance in lung cancer." (PMID 36906674, 2023). "Next, we examined the level of Pdia4 in cancer cells and cancer stromal cells in human lung cancer." (PMID 35170261, 2022). "Furthermore, we also elucidated the mechanism by which Pdia4 exerted its action to facilitate lung cancer development." (PMID 35170261, 2022). "Of note, Pdia4 was highly expressed in CD45+ stromal leukocytes of human lung cancer as evidenced by the co‐localization of both molecules (Merged, Lung cancer)." (PMID 35170261, 2022).
lung carcinoma (continued). "Pdia4 scores indicated that Pdia4 had a low expression level in healthy lung, and this expression was up‐regulated in lung cancer tissues irrespective of their stroma content (Pdia4 score)." (PMID 35170261, 2022). "Although the possibility that the Pdia4/Stat3/Vegf axis also functions in cancer cells could not be excluded, both lines of evidence suggest that targeting Pdia4 in the cancer stroma and cancer cells is a promising two‐pronged approach to treating lung cancer." (PMID 35170261, 2022).
brain cancer (4 papers, 2020 to 2024). A primary or metastatic malignant neoplasm affecting the brain. "It is reported that inhibiting PDIA-4 in brain cancer leads to autophagy-mediated ferroptosis; however, the role of PDIA-4 in endothelial autophagy, apoptosis and function is not studied." (PMID 38612722, 2024).
glioblastoma (4 papers, 2022 to 2025). The most malignant astrocytic tumor (WHO grade IV). "For example, our results align with studies in glioblastoma and cervical cancer, where PDIA4 also acts as an oncogene by promoting proliferation and is associated with poor survival." (PMID 41185082, 2025). "PDIA4 is a potential therapeutic target for the treatment of glioblastoma because it controls the growth of glioblastoma cells by activating the PI3K/AKT/m-TOR pathway and suppressing apoptosis." (PMID 36291587, 2022). "However, the role of PDIA4 in regulating glioblastoma (GBM)-specific pro-angiogenesis is still unknown." (PMID 36997943, 2023).
metabolic syndrome (4 papers, 2017 to 2022). A cluster of metabolic risk factors for CARDIOVASCULAR DISEASES and TYPE 2 DIABETES MELLITUS. "At cutoff point of 15.24 ng/ml, the diagnostic sensitivity and specificity of PDIA4 for the metabolic syndrome were 67 and 72%, respectively, in male patients and 60 and 78%, respectively, in female patients." (PMID 28650993, 2017). "The aims of this study were to investigate the associations of serum PDIA4 with the metabolic syndrome (MetS) and its components in Chinese adults." (PMID 28650993, 2017). "Association of serum PDIA4 with the presence of metabolic syndrome in logistic regression analysis." (PMID 28650993, 2017). "Indeed, circulating levels of PDIA4 were positively associated with metabolic syndrome in adults." (PMID 33806982, 2021). "Sensitivity and specificity of PDIA4 and metabolic syndrome components for the detection of metabolic syndrome." (PMID 28650993, 2017). "Adjusted odds ratios and 95% confidence intervals for the individual components of metabolic syndrome by serum PDIA4 level." (PMID 28650993, 2017). "Our previous report revealed that subjects with metabolic syndrome had significantly higher serum PDIA4 levels than those without metabolic syndrome." (PMID 36619574, 2022).
cervical cancer (3 papers, 2024 to 2025). A primary or metastatic malignant neoplasm involving the cervix. "Additionally, Moreover, elevated levels of PDIA4 were closely linked to worse overall survival in cervical cancer." (PMID 41185082, 2025).
Hyperglycemia (3 papers, 2017 to 2023). An increased concentration of glucose in the blood. "In mouse models and islet mass, deletion of Pdia4, either globally or in β‐cells, led to protection from hyperglycemia, most likely due to a decrease in oxidative stress." (PMID 34542937, 2021). "Consistently, the Pdia4 inhibitor, GHTT, protected against hyperglycemia in the mouse models." (PMID 34542937, 2021).
Insulin resistance (3 papers, 2017 to 2024). Increased resistance towards insulin, that is, diminished effectiveness of insulin in reducing blood glucose levels. "Interestingly, the protein disulfide isomerase family A member 4 (PDIA4) was also jointly upregulated in the 4 donor groups, which is an endoplasmatic stress protein modulating the immune response and insulin resistance in skeletal muscle." (PMID 39050851, 2024).
lung adenocarcinoma (3 papers, 2016 to 2022). A carcinoma that arises from the lung and is characterized by the presence of malignant glandular epithelial cells. "Increased HYOU1 also positively correlated with PDIA4, a known modulator of redox status, which has been shown to promote drug resistance to cisplatin in lung adenocarcinoma." (PMID 27799870, 2016). "ERp72 (PDIA4) and ERp5 (PDIA6) mediate resistance to cisplatin-induced cell death in lung adenocarcinoma." (PMID 29262583, 2017). "Of the 16 distinguishing proteins, 8 were significantly elevated in lung adenocarcinoma (COPG1, STOML2, HYOU1, PDIA4, EPRS, APEX1, LRPPRC and NANS) whereas 8 proteins were significantly decreased in lung adenocarcinoma (SPTB, SPTA1, ANK1, SLC4A1, HBG1 and HBG2)." (PMID 27799870, 2016). "Furthermore, PDIA4 and PDIA6 regulate cisplatin-induced lung adenocarcinoma cell death resistance." (PMID 36291587, 2022).
borderline diabetes (2 papers, 2021 to 2022). "In sharp contrast, Pdia4−/−Leprdb/db mice developed borderline diabetes with average FBG and PBG of around 109 and 289 mg/dl at 24 weeks of age, respectively." (PMID 34542937, 2021). "Following this discovery, the researchers bred mice with the Pdia4 gene knocked out, with Lepr db/db mice and their offspring, which were Pdia 4-/-Lepr db/db, exhibiting borderline diabetes with a later onset than Lepr db/db offspring with the Pdia4 gene present." (PMID 36012526, 2022).
colon cancer (2 papers, 2022 to 2023). "Consistent with previous reports, PDIA1 and PDIA3 were overexpressed in colon cancer tissues in comparison with that in their adjacent tissues, in addition to the overexpressed PDIA2; however, no statistic changes were detected for PDIA4, PDIA5, and PDIA6 expression." (PMID 35860571, 2022).